IDO1 (indoleamine 2,3-dioxygenase 1)
Diseases named in the same sentence as IDO1 in open-access papers (continued):
Sharing a sentence is not in itself a finding about the gene and the disease.
glioblastoma (83 papers, 2012 to 2026). The most malignant astrocytic tumor (WHO grade IV). "Zhai and colleagues established IDO-deficient glioblastoma (GBM) cell lines reconstituted with IDO wild-type or IDO enzyme-null cDNA to assess tumor promotive roles of IDO1 independent of its catalytic activity." (PMID 37876966, 2023). "Our results emphasize the significance of depressing the IDO1-Kyn-AhR axis to activate ferroptosis signaling in the central nervous system as a therapeutic strategy to delay glioblastoma progression." (PMID 39863603, 2025). "Their efforts led to the discovery of NU223612, a potent degrader of IDO-1 in glioblastoma cells (DC50=0.3–0.5 μM)." (PMID 41032705, 2025). "In glioblastoma, studies have largely concentrated on IDO1-mediated immunosuppression and its pivotal role in resistance to immune checkpoint inhibitors." (PMID 40666095, 2025). "IDO-1 in the glioblastoma TME reduces tryptophan levels, which has an immunosuppressive effect and leads to CD8+ T cell exhaustion." (PMID 41403931, 2025). "Several previous studies have investigated the effect of selective IDO1 inhibitors in combination with TMZ in mouse models of glioblastoma." (PMID 39048947, 2024). "Glioblastoma is such a cancer, with both IDO1 and TDO2 expression elevated in most patients, and a strong correlation between TDO expression and poor patient survival." (PMID 39048947, 2024). "Immunohistochemical analysis on glioblastoma TMA cores showed variable cytoplasmic expression of IDO1, IDO2, and TDO2, while AhR showed variable nuclear expression in tumour cells across GBM patients." (PMID 38951170, 2024). "Glioblastomas are notable for featuring increased expression of the tryptophan catabolizing enzymes indole-2,3-dioxygenase-1 (IDO1), and especially tryptophan-2,3-dioxygenase-2 (TDO2)." (PMID 39048947, 2024). "Thereafter, an additional IDO1-based PROTAC was reported to be therapeutically active in a mouse model of glioblastoma." (PMID 38333210, 2024). "Our work shows that glioblastoma patients with high expression of IDO1/2, TDO2 and AhR at diagnosis have a poorer prognosis compared to patients with low expression levels." (PMID 38951170, 2024). "Combination therapies with GITR agonists and IDO1 inhibitors are of interest and a phase-I trial for glioblastoma is currently under progress." (PMID 39001353, 2024). "Our study aimed to examine the expression of the key KP proteins TDO2, IDO1/2 and AhR, in newly diagnosed glioblastoma patients and their correlation with survival." (PMID 38951170, 2024). "There is strong evidence supporting the overexpression of IDO-1 in human glial cell lines, as well as in human glioblastoma biopsies." (PMID 37445721, 2023). "While hypoxia was also shown to induce IDO-1 in DC, an opposite effect was reported in cancer cell lines of ovarian, cervical and glioblastoma origins." (PMID 35211123, 2022). "Other amino acid pathways are being evaluated in clinical trials, such as indoleamine-2,3-dioxygenase-1 (IDO1) inhibitors, epacadostat and indoximod, for tryptophan catabolism in cervical cancer and glioblastoma." (PMID 36276057, 2022). "A study showed the increased therapeutic efficacy of two-fraction radiotherapy in conjunction with IDO1 inhibition in a syngeneic rat glioblastoma model." (PMID 35734424, 2022). "In fact, glioblastoma cells produce EVs containing IDO1, thus suggesting that tumours can exploit both intracellular and extracellular IDO1 to generate an immunosuppressive microenvironment." (PMID 34685679, 2021). "One research has demonstrated increased levels of IDO1 in the glioblastoma cell had positive correlation with human-infiltrating T cells leading to poor prognosis." (PMID 33928021, 2021).
glioblastoma (continued). "Although TDO2 and IDO activity cannot be distinguished based on peripheral blood analysis of KP activity, Riess et al33 showed that glioblastoma multiforme (GBM) tumours had higher TDO2 expression whilst HNSCC tumours mainly presented with IDO1." (PMID 34053179, 2021). "The aim of the study was to investigate therapeutic efficacy of single- or two-fraction radiotherapy in conjunction with IDO1-inhibition in a syngeneic rat glioblastoma model." (PMID 32469935, 2020). "Addition of two-fraction RT to IDO1 inhibition with 1-MT significantly reduced tumor size in animals with glioblastoma." (PMID 32469935, 2020). "Survival analyses were done with animals carrying intracranial glioblastomas comparing two-fraction radiotherapy+IDO1-inhibition to controls." (PMID 32469935, 2020). "The gene analyses of IDO1 expression in human glioblastoma revealed the interesting finding that IDO1 was overexpressed mainly when comparing glioblastoma stem cells to neural stem cells, and not in GBM tissue compared to normal brain tissue." (PMID 32469935, 2020). "Several recent studies have shown that tumor IDO1 expression was correlated with poor prognosis in esophageal cancer, endometrial cancer and glioblastoma." (PMID 32733806, 2020). "In this study, we found that IL-1β also inhibits IDO1 mRNA expression in the A172 glioblastoma, IMR-32 neuroblastoma, and T98G glioblastoma human brain cell lines and in primary human neurons." (PMID 31119110, 2019). "Yet, a recent study demonstrates that post infusion of CAR T cells, tumor specimens in glioblastoma patients have markedly increased expression of many immunosuppressive molecules, particularly IDO1 and FoxP3, and in some cases, IL-10, PD-L1, and/or TGF-β." (PMID 29685162, 2018). "In glioblastoma, the IDO1-mediated response depends on the increase of chemokines like CCL2, able to attract Tregs." (PMID 27174915, 2016). "Their lead compound, NU223612, demonstrated breakthrough efficacy in orthotopic glioblastoma models, achieving robust IDO1 degradation within the intracranial tumor niche - a feat particularly notable given the historically poor penetration of most therapeutic agents into the central nervous system." (PMID 40894232, 2025). "This exceptional potency is complemented by remarkably sustained target suppression, maintaining >90% IDO1 degradation for over 48 h in human glioblastoma cell lines - a critical feature for overcoming the rapid protein turnover often observed in aggressive tumors." (PMID 40894232, 2025). "This study determined to investigate the impact of IDO1 on glioblastoma multiforme (GBM) cells." (PMID 39863603, 2025). "These properties collectively position NU227326 as a potential best-in-class therapeutic candidate, not only for glioblastoma but potentially for other IDO1-dependent malignancies where sustained, complete pathway inhibition is required for optimal therapeutic effect." (PMID 40894232, 2025). "were among the first to demonstrate that glioblastoma cells significantly upregulated the expression of IDO1 and suggested that IDO1 may also contribute to tumor progression by promoting an immunosuppressive phenotype." (PMID 34222022, 2021). "Although recent evidence suggests that there may be value in specifically targeting TDO in the context of glioblastoma, tryptophan metabolism in glioblastoma has primarily been explored in the setting of IDO1/2." (PMID 34222022, 2021). "The expression of IDO1 was increased on gene level in glioblastoma stem cells." (PMID 32469935, 2020). "Analysis of various human cell lines revealed that IL-1β-induced iNOS-dependent reduction of IDO1 mRNA expression occurred in brain cell lines (A172; glioblastoma, IMR-32; neuroblastoma, and T98G; glioblastoma) and liver cell lines (Huh7 and HepG2), but not in other cell lines." (PMID 31119110, 2019).
glioblastoma (continued). "Current investigations are evaluating IDO1 inhibition in specific tumor types with high immunosuppressive microenvironments (e.g., glioblastoma, ovarian cancer) and in earlier disease settings, such as neoadjuvant and adjuvant therapy, where immune modulation may be more effective." (PMID 40894232, 2025). "Thus, these correlations of IDO1 and TDO2 in glioblastoma have led to a hypothesis that IDO1 or TDO2 enzyme inhibition could offer a novel therapeutic approach in the treatment of the disease." (PMID 39048947, 2024). "Glioblastoma (GBM) CSC-derived extracellular vesicles (EVs) containing low amount of PD-L1 represent high levels of IDO1, which is suggestive of multiple layers of immune regulation in such tumor type." (PMID 38144305, 2023). "Similarly, the process of glioblastoma-infiltrating T cells increasing IDO1 expression may be a potential mechanism that contributed to the PD-1 blockade failure." (PMID 30777100, 2019). "Here, we provide data evaluating the novel dual IDO1/TDO2 inhibitor AT-0174, in an orthotopic model of glioblastoma." (PMID 39048947, 2024). "In the current study, the efficacy of a novel dual inhibitor of IDO1 and TDO2, AT-0174, was assessed in an orthotopic mouse model of glioblastoma." (PMID 39048947, 2024). "The present study aimed to investigate the expression of IDO1/2, TDO2, and AhR in glioblastoma tissues of newly diagnosed patients." (PMID 38951170, 2024). "The analysis of comcomitant IDO1/2, TDO2, AhR expression in glioblastoma and its relationship with the tumour environment potentially will help to elucidate this interplay." (PMID 38951170, 2024). "In the current study, the novel and potent dual IDO1/TDO2 enzyme inhibitor AT-0174, was assessed for its capacity to synergise with TMZ in an orthotopic mouse model of glioblastoma." (PMID 39048947, 2024). "We examined IL4I1, IDO1, and AHR expression in the TCGA database and their contribution to glioblastoma and low-grade glioma (LGG) clinical outcome." (PMID 38937431, 2024). "Among them, IDO1, PDCD1, and TGFB1 are promising immune-modulatory targets that are in the focus of current clinical research in glioblastoma." (PMID 35734424, 2022). "IDO1 and TDO2 expression have previously been shown in glioblastoma cell lines 24-29, and in glioblastoma tissue 26, 27, 30-33." (PMID 34646367, 2021). "Especially for immune checkpoints that are less extensively studied in brain tumors, such as IDO1, TIM-3, and CD40, current knowledge is mainly based on research in other malignant brain tumors, such as glioblastoma." (PMID 34771550, 2021). "The expression of select AHR target genes, including AHR itself, positively correlated with TDO2 expression and to a lesser extent with IDO1 expression, pointing towards TCE-mediated AHR activation in glioblastoma." (PMID 34646367, 2021). "The mechanism of tumor invasion and immune resistance involving COL6A3, COL1A1, COL1A2, LRRC15, IDO1, IL-6 and PTGS2 need to be further researched aiming to improve prognosis of aggressive glioblastoma." (PMID 33928021, 2021). "The combination of an IDO-1 inhibitor (epacodostat) and ICI is currently under investigation in a phase I trial assessing solid cancers, including glioblastoma (NCT02327078)." (PMID 32235752, 2020). "IFN-γ stimulation alone resulted in high IDO1 expression levels, while iNOS protein expression was undetected in A172 glioblastoma, IMR-32 neuroblastoma, and T98G glioblastoma cells." (PMID 31119110, 2019). "Further, the correlation analysis of AhR and FTO expression in 169 glioblastoma samples revealed that AhR expression was negatively correlated with FTO expression (R = −0.238, p = 0.008), indicating that IDO1 inhibits FTO activity by promoting AhR expression and nuclear translocation." (PMID 39863603, 2025). "For these reasons, it is proposed that a dual IDO1 and TDO2 inhibitor may offer an improved drug profile for glioblastoma treatment." (PMID 39048947, 2024).
glioblastoma (continued). "Here, we show that IDO-1 is exclusively expressed in macrophage/microglia of the perivascular space, subarachnoid space, and glioblastoma but not in the parenchymal microglia of the brain in humans or murine models." (PMID 34735466, 2021). "We aim to elucidate the distribution pattern of IDO-1+ macrophages/microglia in the human brain tissues, human glioblastoma, APP/PS1 mouse brains, and quinolinic acid model brains and explore the physiological and immunological roles of IDO-1+ macrophages/microglia." (PMID 34735466, 2021). "Glioblastomas exhibit high expression of IDO1, and increased IDO1 expression serves as a negative prognostic factor for patient survival." (PMID 34207158, 2021). "Oppositely, the combination of radiation and PD-1 antibody treatment efficacy required to inhibit IDO1 enzyme activity in non-tumor cells from another study of mouse glioblastoma model." (PMID 35003126, 2021). "This could indicate that IDO1-expression in certain sub-populations of GBM is an important driver of tumor progression and immune suppression in glioblastoma." (PMID 32469935, 2020). "In addition, aminoguanidine treatment inhibited NO production and prevented IDO1 protein level reductions in all IFN-γ- and IL-1β-costimulated A172 glioblastoma, IMR-32 neuroblastoma, and T98G glioblastoma human brain cell lines." (PMID 31119110, 2019). "Interestingly, IL-1β stimulation in all tested brain cell lines (A172; glioblastoma, IMR-32; neuroblastoma, and T98G; glioblastoma) severely reduced IFN-γ-induced IDO1 mRNA expression levels in a manner similar to or greater than that of the liver cell lines." (PMID 31119110, 2019). "In previous experiments with human glioblastoma cells and alveolar epithelial cells, we found that TNFα and IL-1β, respectively, did not induce IDO1 directly, but required IFN-γ to synergistically induce IDO1." (PMID 31267172, 2019). "Interestingly, in a glioblastoma model, IDO-1 increases Treg cell recruitment and does not appear to be affected by Trp metabolism, suggesting that IDO1 can influence Treg cell development through enzymatic activity." (PMID 40696413, 2025). "Further studies have indicated that non-enzymatic functions of IDO-1 involving up-regulation of expression levels (e.g. complement factor H) may be the reason for therapy failure, especially in glioblastoma treatment." (PMID 41032705, 2025). "Furthermore, treatment of IFN-γ in glioblastoma cells increases expression of PD-L1 and indoleamine 2,3-dioxygenase 1 (IDO1) in EVs, without affecting their size or frequency." (PMID 39267734, 2024). "Nevertheless, the recent studies revealed that TDO could be involved in modulating antitumor immune responses and the antitumor immunotherapy efficacy, but it did not colocalize with IDO1, at least, in human glioblastoma." (PMID 35003126, 2021). "Interestingly, treatment with the IDO-1 enzyme inhibitor BGB-5777, combined with anti-PD1 antibody, as well as radiotherapy in a mouse model of glioblastoma, increased the absolute numbers of CD8 T cells in the tumor and increased survival, when compared to monotherapy with either single agent." (PMID 32235752, 2020). "However, while these results showed some promise, glioblastoma is especially notable for high TDO2 expression, and IDO1 inhibition in the absence of TDO2 inhibition may well have limited efficacy of these compounds in treating glioblastoma." (PMID 39048947, 2024). "Here, we find that both human and mouse macrophages/microglia of the perivascular and subarachnoid space and in glioblastoma (GBM) expressed IDO-1 but not macrophages/microglia of parenchyma." (PMID 34735466, 2021). "To verify whether this peculiar crosstalk between mTOR and IDO1 observed in DAOY cells could be extended also to other high-grade or low-grade brain tumors, we evaluated the expression of the two molecules by WB on 4 glioblastoma and 2 ganglioglioma tissue specimens." (PMID 27174915, 2016).
ovarian carcinoma (79 papers, 2009 to 2026). A malignant neoplasm originating from the surface ovarian epithelium. "Previous data have manifested that IDO1 was highly expressed in multiple cancer tissues including ovarian cancer, and that a high expression level was associated with poor prognosis." (PMID 36233312, 2022). "Several studies have confirmed IDO1 expression in various cancer types, including lung, colorectal, prostate, breast, and ovarian cancers, in association with poor patient prognosis." (PMID 34769098, 2021). "In a study of non-small cell lung cancer, ovarian cancer and other tumor tissues, IDO1 was found to be associated with malignancy degrees of the tumors." (PMID 30314496, 2018). "Afterward, univariate Cox regression analysis was performed to evaluate the prognostic value of each tryptophan metabolism-related gene in the TCGA ovarian cancer cohort, with IDO1, ALDH3A2, HADHA, OGDHL associated with risk values, and CAT, WARS1 involved in protective factors." (PMID 38468343, 2024). "Similarly, IDO1—an enzyme with an immune tolerance effect—has been reported to regulate peritoneal dissemination and is linked to poorer survival in ovarian cancer patients." (PMID 34094977, 2021). "GBP1 protects ovarian cancer cells from paclitaxel by associating with beta-tubulin, altering cytoskeletal dynamics to sequester the drug within the microtubule network, and partnering with IDO-1 to reduce apoptosis—a dual shield against cell death that enhances chemotherapeutic resistance." (PMID 40564939, 2025). "Similarly, in ovarian cancer, increased expression of IDO1 is associated with improved prognosis." (PMID 39672307, 2024). "IDO1+ ovarian cancer (OC) cells were found to be mediated by exosomes to promote endothelial cell mitophagy." (PMID 40821701, 2025). "IDO1 expression promotes ovarian cancer progression through AhR activation, inducing PD‐1 expression in T cells." (PMID 41332472, 2025). "In ovarian cancer, GBP1 protects cells from paclitaxel by associating with beta-tubulin and indoleamine 2,3-dioxygenase 1 (IDO-1), enhancing survival under chemotherapeutic stress and enabling drug resistance." (PMID 40564939, 2025). "Cancer-associated fibroblasts (CAFs) contribute to immunosuppression in the ovarian cancer microenvironment, partly through upregulation of indoleamine 2,3-dioxygenase 1 (IDO1)." (PMID 41078340, 2025). "Studies indicated that IDO1 inhibitors modulate the tumor immune microenvironment, encompassing ovarian cancer." (PMID 38468343, 2024). "To investigate the effect of epacadostat on endogenous IDO1, we resorted to the human ovarian cancer cell line SKOV-3 that constitutively expresses the highest level of IDO1 transcript among different human ovarian cancers." (PMID 38333210, 2024). "In the current study, IDO1 RNA expression was found to vary across tumor types and, in particular, uterine and ovarian cancers had high levels of IDO1 RNA expression." (PMID 38632994, 2024). "Our recent study in ovarian cancer demonstrated that TDO2/IDO1 targeting alone attenuates PD-L1 expression." (PMID 39311710, 2024). "High IDO1 transcripts were more frequent in uterine (54.2%) and ovarian cancer (37.2%) but varied between and within malignancies." (PMID 38632994, 2024). "Consistently, ELISA assay showed that EVs acquired from IDO1-overexpression ovarian cancer cells significantly increased the L-kyn level in the endothelial cells, and these effects were reversed by treatment with GW4869, a classical EV inhibitor." (PMID 38468343, 2024). "Consistently, IDO1-overexpression ovarian cancer cell-derived EVs increased the endothelial mito-ROS, while IDO1-knockdown ovarian cancer cell-derived EVs suppressed the endothelial mito-ROS." (PMID 38468343, 2024). "A mitochondrial membrane potential assay with TMRE staining revealed that IDO1-overexpression ovarian cancer cell-derived EVs inhibited endothelial mitochondrial membrane potential." (PMID 38468343, 2024).